PCLO (piccolo presynaptic cytomatrix protein)
Diseases named in the same sentence as PCLO in open-access papers (continued):
Sharing a sentence is not in itself a finding about the gene and the disease.
lymphoma (3 papers, 2015 to 2025). A malignant (clonal) proliferation of B- lymphocytes or T- lymphocytes which involves the lymph nodes, bone marrow and/or extranodal sites. "Mutations in PCLO have been found in lymphoma, several types of solid tumors, and one report of myeloma." (PMID 36230837, 2022). "The recurrent nature of the PCLO mutations, which was described in a recent report (35% in lymphomas), implicates the potential oncogenic roles of this gene." (PMID 26336987, 2015).
mental disorder (3 papers, 2013 to 2023). A disease that has its basis in the disruption of mental process. "Certain single-nucleotide polymorphisms of the Piccolo-encoding gene PCLO are reported to be associated with mental disorders." (PMID 34206873, 2021). "In such an effort to search a gene that related to mental disorders, PCLO was identified as an overexpressed gene in the nucleus accumbens of mice subjected to repeated methamphetamine treatment, which can cause severe mental disorders." (PMID 24167553, 2013).
glioblastoma (2 papers, 2021 to 2022). The most malignant astrocytic tumor (WHO grade IV). "In the mesenchymal subtype of glioblastomas, PCLO mutations have been shown to be associated with poor prognosis, but its association with the prognosis of DLBCL has not been reported." (PMID 36465410, 2022).
lung adenocarcinoma (2 papers, 2018 to 2021). A carcinoma that arises from the lung and is characterized by the presence of malignant glandular epithelial cells. "We found that the mutation rates of TTN, PCLO, RYR3, and LRP2 in human lung adenocarcinoma were 41%, 16%, 14% and 11%, respectively, but the mutation rates of other mutant genes were <10%." (PMID 34858801, 2021).
Alzheimer disease (1 paper, 2025). A progressive, neurodegenerative disease characterized by loss of function and death of nerve cells in several areas of the brain leading to loss of cognitive function such as memory and language. "The results of GSEA based on the TMB data showed that the PCLO mutation may be associated with the activation of ‘Alzheimers disease’, ‘Huntingtons disease’, ‘oxidative phosphorylation’, ‘Parkinsons disease’, and the ‘proteasome’ pathway." (PMID 40699825, 2025).
Anxiety (1 paper, 2025). Intense feelings of nervousness, tension, or panic often arise in response to interpersonal stresses. "Therefore, PCLO could be an attractive gene to be investigated in our lbx1a and lbx1b mutant lines to further analyze its impact on anxiety-related phenotypes." (PMID 41440000, 2025). "Interestingly, we identified 13 overlapping genes regulated in the overexpression experiment and only three genes regulated in the lbx1a(−/−) mutant line (NPM1, PCLO, and FADS2), which are candidate genes from anxiety GWAS studies." (PMID 41440000, 2025).
autism (1 paper, 2023). Persistent deficits in social interaction and communication and interaction as well as a markedly restricted repertoire of activity and interest as well as repetitive patterns of behavior. "Two genes (SRRM2 and AKAP11) were newly implicated as SCZ risk genes, and one gene (PCLO) was identified as shared by individuals with SCZ and those with autism." (PMID 36914870, 2023).
Cerebellar atrophy (1 paper, 2024). Cerebellar atrophy is defined as a cerebellum with initially normal structures, in a posterior fossa with normal size, which displays enlarged fissures (interfolial spaces) in comparison to the foliae secondary to loss of tissue. "PCH3 is caused by mutations in the PCLO gene and clinical features exist of facial dysmorphism, optic atrophy, cerebellar atrophy, and neonatal hypotonia." (PMID 38622473, 2024).
colon adenocarcinoma (1 paper, 2017). "Once the somatic mutations of all genes in colon adenocarcinoma were analyzed by COSMIC, the result showed that the majority of top 20 genes with somatic mutations are mRNA over expression (18/20) and CNA gain, except 2 genes (PCLO with high methylation and APC with high point mutation)." (PMID 29108255, 2017).
endometrioid endometrial carcinoma (1 paper, 2022).
lung carcinoma (1 paper, 2023).
lymph node metastasis (1 paper, 2020). "PCLO overexpression is associated with lymph node metastasis, poor OS and poor disease free survival (DFS) in ESCC." (PMID 33898301, 2020).
metastatic tumor (1 paper, 2016). "Unique mutations in PCLO and CSMD3 in P3A and P3B, respectively and FLG, MLL3 and SPEN in metastatic tumor M3A are listed in the branches." (PMID 27034009, 2016).
optic atrophy (1 paper, 2024). A disorder characterized by loss of optic nerve fibers. "PCH3 related to a homozygous mutation in the PCLO gene is defined associated with optic atrophy and thin corpus callosum on MRI." (PMID 38622473, 2024).
oral cancer (1 paper, 2025).
T-cell lymphomas (1 paper, 2025). "NEB and PCLO variants were infrequent in T-cell lymphomas, including T-LGLL." (PMID 40202536, 2025).
thymoma (1 paper, 2025). A neoplasm arising from the epithelial cells of the thymus. "The most frequently mutated genes within each subtype were as follows: PCLO (27%), POT1 (27%), and STAT3 (27%) in idiopathic PRCA; STAT3 (20%), DNMT3A (10%), and CUX1 (10%) in thymoma-associated PRCA; and STAT3 (54%) and TET2 (12%) in LGLL-associated PRCA." (PMID 40202536, 2025).
tumor (28 papers, 2014 to 2026). "Similarly, mutations in CSMD3, LRP1B, and PCLO are closely associated with tumor development and progression." (PMID 41235252, 2025). "Meanwhile, a mounting body of evidence suggests that mutations in PCLO are associated with tumor sensitivity to etoposide, implying that the sensitivity to chemotherapy may be different in various risk subgroups." (PMID 35205097, 2022). "Among the primary tumor samples, AKAP9, KDM2B, MAGED1, MKI67, PCLO, and TRAF1 mutations were identified." (PMID 41614915, 2026). "Among the 95 primary tumor samples, AKAP9, KDM2B, MAGED1, MKI67, PCLO, and TRAF1 mutations were identified as single-occurrence events and were absent in the metastatic samples." (PMID 41614915, 2026). "In contrast, the RRGS-High subgroup is characterized by mutations in genes such as MUC16, PCLO, and CSMD3, which are commonly associated with more aggressive tumor features and poorer outcomes." (PMID 39668832, 2024). "The 1° tumor had eight variants in MKI67, PRKN, PCLO, POLE, CDKN1C, IGSF3, and MED12 genes, which were also present in the brain and spine metastatic cell lines but not present in the parental cell line." (PMID 36900209, 2023). "Several genes (including BCR, PCLO, ATXN3, PABPC3, and FADS6) were mutated in two or more PDX tumours." (PMID 33144587, 2020). "Moreover, primary tumor samples had exclusive mutations in AKAP9, KDM2B, MAGED1, MKI67, PCLO, and TRAF1." (PMID 41614915, 2026).
cancer (17 papers, 2014 to 2026). A tumor composed of atypical neoplastic, often pleomorphic cells that invade other tissues. "In the PCLO mutation group, several cancer-related pathways, such as the ‘proteasome’ and ‘oxidative phosphorylation’ pathways, were enriched." (PMID 40699825, 2025). "Together with FMN2, PCLO formed a positive feedback in the evolutionary tree in stage IV, suggesting their roles in accelerating cancer evolution." (PMID 29463849, 2018). "According to the authors, large proteins (>4000 amino acids) are found to be mutated at a significant frequency, thus making some of them falsely associated with various cancers, e.g., MUC16 and PCLO in DLBCL." (PMID 27164089, 2016). "Besides, TRPM2/PCLO was a co-occurring gene pair in the IFNGrGS score-low group, indicating a possible synergistic perturbation of different cancer-related biological processes." (PMID 34566988, 2021). "It should be noted that among the most frequently mutated genes in our results, there are several constantly found mutated in cancer (e.g., PCLO, TTN) that are considered non-oncogenic." (PMID 29596374, 2018). "The following most altered cancer genes were LRP1B (26%), PIK3CA (24%), CDKN2A (24%), PTPRD (15%), RB1 (13%), PDE4DIP (13%), PCLO (11%), KRAS (11%), FAT1 (10%), and RELN (10%), and these results partially overlap with the most altered genes depicted in the experimental cohort." (PMID 35330454, 2022).
neurological disorders (1 paper, 2025). "PCLO encodes the Piccolo protein, which plays a critical role in synaptic function and neurological disorders." (PMID 42038819, 2025).
PCLO also shares sentences with these, for which no sentence is quoted: glioma (3 papers); hepatocellular carcinoma (3); colon cancer (2); attention deficit-hyperactivity disorder (1); blood cancer (1); breast carcinoma (1); chronic hepatitis (1); developmental delay (1); endometrial cancer (1); epilepsy (1); Huntington disease (1); Hypertonia (1); Hypotonia (1); liver (1); metabolic syndrome (1); microcephaly (1); migraine headache (1); myeloid leukemia (1); myeloma (1); neurodevelopmental disorder (1); oral squamous cell carcinoma (1); Parkinson disease (1); pontocerebellar hypoplasia type 3 (1); small cell lung carcinoma (1); stomach adenocarcinoma (1); type 1 diabetes mellitus (1); type 2 diabetes mellitus (1).